PAK1 (p21 (RAC1) activated kinase 1)
Diseases named in the same sentence as PAK1 in open-access papers (continued):
Sharing a sentence is not in itself a finding about the gene and the disease.
cancer (continued). "The overexpression of PAK1, notably prevalent in various malignant neoplasms, such as pancreatic, breast, and renal cancers, has prompted the development of PAK1-3 inhibitors, which have been demonstrated to ameliorate this condition." (PMID 40332759, 2025). "The signaling pathway involving Rac1 and PAK1 frequently exhibits overactivation across various cancer types." (PMID 40867609, 2025). "PAK1 has been implicated in cytoskeletal remodelling and endothelial barrier regulation, whereas PAK4 is linked to cancer cell survival, stemness, and therapy resistance." (PMID 41294859, 2025). "The serine/threonine kinase PAK1 serves as a mediator of cytoskeletal reorganization and cancer-related signaling downstream of the small GTPases." (PMID 41265809, 2025). "Inhibition of PAK1 activity has been widely described to significantly reduce cell proliferation, promote apoptosis in various cancer cell types, and reduce tumor size and extend the lifespan of treated animals." (PMID 41516310, 2025). "In PDA, PAK1 was shown to inhibit cancer cell apoptosis, activate pancreatic stellate cells and down-regulate intra-tumoral CD4 + and CD8 + T cell infiltration." (PMID 38797819, 2024). "PAK1 is a key downstream effector of the small GTPase Rac1, which plays important roles in cancer cell migration and invasion." (PMID 38227562, 2024). "Clinical research has demonstrated that PAK1 not only participates in the tumorigenicity of diverse cancers but also modulates autophagy levels through the Akt/mTOR or Erk/mTOR signaling pathway." (PMID 38956466, 2024). "P21-activated kinase 1 (PAK1), previously reported to have oncogenic activity in various types of cancer, was found to regulates the number of epidermal stem cell by altering LCs properties and functions in skin carcinogenesis." (PMID 38229178, 2024). "Our results show that TonEBP plays an important role in IL-1β–induced cancer cell migration and invasion and that some of these effects proceed via the regulation of PAK1 expression in A549 cancer cells." (PMID 38188678, 2023). "Growth factor–induced MET activates both PI3K, which activates through stathmin and PAK1 via Paxillin and promotes cancer progression." (PMID 36830998, 2023). "We review, clarify, and connect dysregulated pathways with dysregulated proliferation and differentiation in cancer and NDDs and highlight PAK1 role in brain development and MAPK regulation." (PMID 37124926, 2023). "Treatment with IPA3, a PAK1-phosphorylation blocker, significantly reduced cancer cell migration and invasion." (PMID 38188678, 2023). "This suggests that IL-1β–induced ERK and NF-κB signaling induces cancer cell migration and invasion by regulating PAK1 phosphorylation." (PMID 38188678, 2023). "Second, AKT regulates cancer cells by PAK1/ATF2/miR-132 signaling axis and PRKAG3 is a target gene of miR-132." (PMID 36766336, 2023). "It is also worth mentioning that PAK1 can be regulated indirectly by preventing its activation by cancer-relevant small GTPases." (PMID 37830586, 2023). "It was suggested that this involves OIS, cell cycle arrest at the G1/S phase, and downregulation of cyclin-A, cyclin-D1, and cyclin-E, especially in cancers arising from PAK1-expressing tissues, such as brain, pancreas, colon, or ovary." (PMID 37124926, 2023). "Among the QTL for the number of seeds per pod, p21-activated kinases 1 (PAK1) PAK1 P21 mediates cell proliferation, migration, and survival in animal cells and is an effective therapeutic target for cancer treatment." (PMID 38140482, 2023). "There is sufficient evidence to implicate PAK1 in the response of cancer cells to genotoxic impacts, including those delivered in the course of therapy." (PMID 37830586, 2023). "PAK1 (p21-activated kinase 1) has been shown to be upregulated in many cancers and is activated through phosphorylation by Cdc42 and activates LIMK1." (PMID 37464436, 2023).
cancer (continued). "This suggests that IL-1β induces cancer cell migration and invasion via the PAK1 pathway, downstream of ERK, p38, and NF-κB signaling." (PMID 38188678, 2023). "In a variety of human malignancies, overexpression of activated PAK1 is known to associate with 'addiction' to this kinase, rendering increased sensitivity to PAK inhibition, especially in PAK1-amplified cancers." (PMID 37564209, 2023). "PAK1 has been shown to play a role in cancer initiation and progression by regulating cancer growth, angiogenesis, metastasis, survival, tumor immunity and metabolism and drug resistance." (PMID 38004560, 2023). "The next set of studies demonstrated the overexpression of PAK1 in human cancer specimens for the first time." (PMID 36830998, 2023). "For example, a recent study demonstrated that a small peptide, RMR, inhibits phosphorylation of RUNX3 at T209 by PAK1, effectively suppressing cancer cell proliferation and cancer formation." (PMID 36899853, 2023). "CDC42 was proved to regulate EMT and cancer metastasis, and activate PAK1 (a serine/threonine protein kinase) which was involved in various tumor signaling pathways including MAPK." (PMID 36849460, 2023). "We investigated the phosphorylation of PAK1, a signaling molecule that induces cancer cell migration." (PMID 38188678, 2023). "PAK1 is positioned amidst multiple intracellular signaling pathways, including the ones that control cancer-relevant traits such as proliferation, resistance to apoptosis, invasiveness, motility, etc.." (PMID 37830586, 2023). "Despite this knowledge, the clinical development of PAK1 inhibitors for cancer therapy was a challenge." (PMID 37190165, 2023). "p21-activated kinase 1 (PAK1), an important signaling molecule, induces cell migration and invasion in several carcinomas." (PMID 38188678, 2023). "Pak1 has also been shown to play a role in numerous pathological conditions, such as cardiovascular disease, neurodevelopmental disorder, and cancer." (PMID 39899001, 2022). "Knockdown of ARHGAP15 resulted in activation of PAK1/2 and indirectly promoted Rac activation, thereby enhancing cancer-promoting signal transduction." (PMID 36168627, 2022). "PAK1 was previously reported to regulate cancer cell metabolism and proliferation and BCAT1 is implicated in cancer metabolic reprogramming, tumour metastasis and drug resistance." (PMID 35811334, 2022). "On the one hand, PAK1 is overexpressed in many cancers and positively correlates with promotion of cell survival, invasion and metastasis, and drug resistance." (PMID 35206009, 2022). "PAK1, which is located on chr11, was frequently overexpressed or excessively activated in almost all cancer types and is involved in nearly every stage of cancer progression." (PMID 35811334, 2022). "Cytoplasmic p120ctn constitutively activates ERK in the downstream signaling of EGFR through the activation of PAK1, and promotes cancer cell resistance to TKIs." (PMID 36230657, 2022). "In support of these findings, HCC patients with higher levels of RAC1, CDC42, and PAK1 show worse overall survival, which can be attributed to enhanced macropinocytosis and resistance to cancer therapy." (PMID 35287706, 2022). "It has been shown that CK2α colocalizes with PAK1 through the association with CKIP-1 at the plasma membrane as a response to EGF, and CK2α phosphorylates PAK1, promoting its cancer-related functions." (PMID 36429067, 2022). "Increasing evidence shows that PAK1 is frequently amplified or overexpressed in patients with a variety of malignant tumors, such as ovarian, hepatocellular carcinoma, breast, and colorectal cancers." (PMID 35566098, 2022). "In this study, we aimed to screen novel PAK1 inhibitors from natural compounds which have great potential in cancer therapy because of their safety, low cost, and oral bioavailability." (PMID 35566098, 2022).
cancer (continued). "The emerging role of PAK1 as potential therapeutic target in cancer was recently reviewed comprehensively, elaborating interesting facts and classical evidences to understand its role in many oncogenic signaling pathways." (PMID 35186026, 2022). "In recent years, more and more scholars have focused on cancer-related molecular markers and gene targets, such as PAK1 and SOX8." (PMID 36230738, 2022). "PAK1 protein, a family of serine/threonine p21-activated kinases, is a regulator of cancer-inflammation signaling leading to the activation of STAT3 and NF-κB." (PMID 36012284, 2022). "Previous studies have demonstrated the significance of PAK1 in multiple cancer types, which participated in cell survival and drug resistance." (PMID 35811334, 2022). "Of note, some studies suggested that P21 (RAC1) activated kinase 1 (PAK1) is an oncogenic serine/threonine kinase that is dysregulated in various cancers." (PMID 35500159, 2022). "In the survival analysis of pan-cancer patients, high expression of PAK1, PAK2, PAK4, and PAK6 as well as the low expression of PAK7 was mainly associated with poor prognosis of tumor patients." (PMID 36064705, 2022). "In human tumors, the overexpression and overactivation of PAKs kinases, especially PAK1 and PAK4, are usually associated with cancer, because both kinases are found to be elevated at DNA, RNA, or protein levels in many types of cancer." (PMID 36064705, 2022). "It is also reported that a co-repressor of Notch signaling pathway was phosphorylated by PAK1 at S3486 and T3568 to inhibit Notch targeted gene activation and regulate cancer fate." (PMID 33796531, 2021). "RAC1, a key regulator of multiple oncogenic pathways including mTORC1/2 and PAK1/2/3 among others 22 is emerging as a significant therapeutic target in different cancers." (PMID 34803511, 2021). "Upregulation of proteins involved in focal adhesion, such as PAK1 indicate the coordinated activation of cancer cell invasion in response to anti-androgen treatment." (PMID 33572476, 2021). "Of those, PAK1 is overexpressed in many cancers and considered to be a major chemotherapeutic target." (PMID 34471161, 2021). "PAK1 inhibitor combined with chemotherapy gemcitabine synergistically inhibited cancer cell proliferation and tumor growth in pancreatic cancer." (PMID 33796531, 2021). "We previously synthesized 1,2,3-triazolyl ester of ketorolac (15K) through click chemistry technique, which exhibits significant anti-cancer effects via inhibiting PAK1." (PMID 34471161, 2021). "PAK1 inhibits TGF-β expression and TGF-β in turn to enhance PAK1 activation to promote cancer development." (PMID 33796531, 2021). "Mechanically, overexpression of ARHGAP25 inactivated AKT/mTOR signaling pathway by regulating Rac1/PAK1 signaling, which was in line with the results from the Gene set enrichment analysis on The Cancer Genome Atlas dataset." (PMID 33994864, 2021). "Current studies argue that IVM degrades PAK1 in cancer cells through the ubiquitination pathway, thereby inactivating the AKT-mTOR pathway, which is the key negative regulatory pathway of autophagy." (PMID 33996598, 2021). "In conclusion, the effects of PAK1 on immunity and metabolism can regulate the progression of cancer in a variety of situations." (PMID 32863957, 2020). "Over the last 20 years, researchers have increasingly recognized the role of PAK1 in the progression of cancer." (PMID 32863957, 2020). "To examine the role of PAK1 in the three p27‐mislocalized cancer cell lines, we silenced the PAK1 expression in these cell lines." (PMID 31872963, 2020). "PAK1 participates in almost every stage of a cancer cell and in every indispensable signal pathway, including EGFR/HER2/MAPK, Wnt/β-catenin, JNK/c-jun, NF-κB, cell cycle, apoptosis, autophagy and others, such as TGF-β and STAT5 signaling." (PMID 32863957, 2020). "Activated PAK1 fine-tuning the Wnt/β-Catenin pathways contribute to regulating cancer proliferation and metastasis." (PMID 32863957, 2020).
cancer (continued). "PAK1 participates in multiple signaling pathways of cancer development through regulating various substrates." (PMID 32863957, 2020). "We also discuss the suitability of PAK1 as an anti-cancer drug target and recent advances in the development of PAK1 inhibitors based on their structure types." (PMID 32863957, 2020). "Considering that PAK1 plays an important role in the network of cancer-dependent proteins, selective co-regulation of these proteins is also a good solution." (PMID 32863957, 2020). "Collectively, PAK1 activation makes cancer cells more robust and invisible to the immune system, thus paving the way for further proliferation." (PMID 32863957, 2020). "Recently PAK1 has attracted wide attention due to its important role in regulating the skeleton and the movement of cancer cells." (PMID 32863957, 2020). "It is worth noting that the crosstalk between PAK1 and TGFβ pathway is also important in cancer proliferation, angiogenesis, EMT and metastasis regulation." (PMID 32863957, 2020). "We can develop a treatment strategy targeting PAK1 PPI network that is personalized according to the molecular characteristics of particular cancer." (PMID 32863957, 2020). "We also summarize the reported PAK1 small-molecule inhibitors based on their structure types and their potential application in cancer." (PMID 32863957, 2020). "Previous studies have shown that p27 mislocalization occurs in multiple cancer types and the protein mislocalization correlates with poor prognoses, but the role of PAK1 in these p27‐mislocalized cancers is still elusive." (PMID 31872963, 2020). "The activation of PAK1 allows it to participate in cancer cell proliferation pathways to inhibit apoptosis and facilitate the survival of cancer cells." (PMID 32863957, 2020). "Although the multi-faceted promotion of cancer by PAK1 is disturbing, it also provides an opportunity for the treatment of most PAK1-dependent cancers." (PMID 32863957, 2020). "As PAK1 is a well-characterized promoter of the progression of cancer and a criminal in cancer development, and PAK1 inhibition is a good target for many cancer treatments." (PMID 32863957, 2020). "All these findings indicate PAK1 is a potential therapeutic target for diverse cancers including ESCC." (PMID 32237037, 2020). "Over the last couple of years, many PAK1 inhibitors have been developed and tested in cellulo for their anti-cancer potential." (PMID 33066011, 2020). "PAK1 stimulates cancer cell proliferation and survival by activation of both ERK- and AKT-dependent pathways." (PMID 33126623, 2020). "Increasingly, studies have revealed the important role of PAK1-regulated EGFR/HER2/MAPK pathways in cancer." (PMID 32863957, 2020). "With the development of more specific and clinically applicable PAK1 inhibitors, future animal studies will be warranted to evaluate the therapeutic effects of PAK1 inhibitor strategies in various cancers." (PMID 31872963, 2020). "Recently, the PAK1 has emerged as a potential therapeutic target in cancer due to its role in many oncogenic signaling pathways." (PMID 32863957, 2020). "PAK1 have emerged as a promising oncology targets and attracted a lot of pharmacologist interest due to its critical roles in cancers." (PMID 32752894, 2020). "Next, we will further discuss the specific mechanism by which PAK1 participates in the course of the life of cancer cells." (PMID 32863957, 2020). "Given the extensive cancer-related functions of PAK1, significant efforts have been made to develop PAK1 inhibitors from pharmaceutical and academic settings." (PMID 32863957, 2020). "Our findings also provide a basis for harnessing PAK1 as an actionable therapeutic target to inhibit the metastatic progression of OS and other cancers with p27 mislocalization." (PMID 31872963, 2020). "Active pharmaceutical efforts are also in progress to identify more effective and specific small‐molecule inhibitors of PAK1 for cancer treatment." (PMID 31872963, 2020).
cancer (continued). "As a core regulator of cell proliferation and metastasis networks, PAK1 plays a prominent role in cancer drug resistance." (PMID 32863957, 2020). "The inhibitory effect of PAK1 on apoptosis is also indispensable during the entire metastasis process 60, and the inhibition of apoptosis also ensures the survival of cancer cells to the greatest extent." (PMID 32863957, 2020). "In 2013, other new aminopyrazole-based PAK1 inhibitors for cancer treatment and hyper-proliferative disorders were reported by Genentech." (PMID 32863957, 2020). "Both PAK1 and cannabinoids can exert their effects on cancer by modulation of tumour immune response." (PMID 33126623, 2020). "Since PAK1 stimulates cancer cell proliferation, migration/invasion, and survival via ERK- and AKT-dependent pathways, it is interesting to determine if cannabinoids act through PAK1 signalling pathway(s)." (PMID 33126623, 2020). "In this paper, we review PAK1's roles in cancer, including its structure and autoactivation mechanism; its essential function from the onset, progression to metastasis, and even drug resistance in cancer; endogenous regulators; and cancer-related pathways." (PMID 32863957, 2020). "Except for TGFβ signaling, Notch, Hippo/YAP and STAT5 signaling pathways are also involved in PAK1-regulated cancer progression." (PMID 32863957, 2020). "Cancer cells can further metastasize and deteriorate under the programming of a signal network regulated by PAK1." (PMID 32863957, 2020). "In prostate cancer, PAK1 was found to inhibit TGFβ expression to promote cancer cell growth and migration." (PMID 32863957, 2020). "Because PAK4 has been well summarized, including its signaling, regulation, and specificity 8, here, we focus our discussion on PAK1 in cancer." (PMID 32863957, 2020). "PAK1 has been reported to play a vital role in variety of disorders such as cancer, Alzheimer's disease, diabetes, and neurofibromatosis." (PMID 33124146, 2020). "In particular, PAK1 has several well-documented roles, both kinase-dependent and kinase-independent, in cancer-related processes, such as cell proliferation, adhesion, and migration." (PMID 31748572, 2019). "The immunofluorescence analysis with anti-PAK1 and anti-Stat3 in cancer cells indicated that PAK1 and Stat3 colocalize in the nucleus." (PMID 31658701, 2019). "We found that invadopodia disassembly in response to chemotactic factors, as mediated by PAK1, is important for directing cancer cell extravasation in microenvironments and is a worthy anti-metastasis target." (PMID 30651600, 2019). "In summary, PAK1 is responsible for guided cancer cell extravasation because invadopodia are able to respond to specific stimuli before prompting the cell to undergo transendothelial migration." (PMID 30651600, 2019). "Dysregulation through phosphomimics or PAK1-CA led to small dynamic adhesions and rapid cell migration reminiscent of highly migratory cancer cells." (PMID 31391572, 2019). "PAK1 and PAK4 levels are highly elevated in many cancers, and the other members of the PAK family are also linked to cancer." (PMID 31658701, 2019). "Several attempts have been made to specifically target PAK1 in cancer, however, its catalytic pocket is large and highly flexible, in addition to its highly mobile N-terminal lobe, which presented a challenge in preventing specific PAK inhibitors." (PMID 31660987, 2019). "p21-activated kinase 1 (PAK1) plays a fundamental role in promoting the development and progression of several cancers and is a potential therapeutic target." (PMID 30971268, 2019). "As a migration and invasion inhibitory protein and a metastasis suppressor, MIIP was reported to bind to and antagonize the function of diverse effectors, including IGFBP-2, HDAC6 and PAK1, depending on different molecular context in different cancer types." (PMID 31092266, 2019).